HOXC6 (homeobox C6)
Diseases named in the same sentence as HOXC6 in open-access papers (continued):
Sharing a sentence is not in itself a finding about the gene and the disease.
cervical carcinoma (15 papers, 2018 to 2025). A carcinoma arising from either the exocervical squamous epithelium or the endocervical glandular epithelium. "For instance, high expression levels of HOXC8 and HOXC6 by immunohistochemistry were associated with poorer prognosis in a cohort of patients with esophageal squamous cell carcinoma, and increased gene expression was associated with worse outcome in cervical carcinoma." (PMID 32366326, 2020). "Studies have shown that the silencing of HOXC6 suppressed EMT via the inhibition of the TGF-β/Smad signaling pathway in cervical carcinoma cells." (PMID 33413548, 2021). "HOXC6 was overexpressed in multiple solid tumors, like hepatocellular carcinoma, cervical carcinoma (CC), head and neck cancer and GI carcinoids 47-50." (PMID 33123277, 2020). "In cervical cancer, enhanced HOXC6 expression leads to cervical cancer cell proliferation, cell cycle progression, colony formation anchoring and xenograft tumor growth." (PMID 32509568, 2020). "As reported in previous studies of other types of cancer, HOXC6 exhibited the biological function of matrix remodelling, cell migration, invasion and metastasis in other types of malignancies, such as laryngeal cancer, cervical carcinoma and lung cancer." (PMID 35488304, 2022). "Silencing of HOXC6 is capable of inhibiting epithelial-mesenchymal transition (EMT) through the inactivation of the transforming growth factor-beta (TGF-β)/Smad signaling pathway in cervical carcinoma cells." (PMID 32171324, 2020). "However, the expression of HOXC6 and its clinical significance remains unclear in cervical carcinoma (CC)." (PMID 30559605, 2018). "Similarly, in cervical cancer, BBOX1-AS1 can interact with HuR, enhancing the mRNA stability of HOXC6, subsequently upregulating the HOXC6 protein expression, and promoting cancer cell proliferation, migration, and invasion abilities." (PMID 37925403, 2023). "A finding similar to ours was that HOXC6 gene silencing delays EMT (reflected by decreased N-cadherin and Vimentin expression and increased E-cadherin expression) through the inhibition of the activation of TGF-β/Smad signaling pathway in cervical carcinoma cells." (PMID 32171324, 2020).
colorectal cancer (14 papers, 2016 to 2025). A primary or metastatic malignant neoplasm that affects the colon or rectum. "In colorectal cancer, for example, high HOXC6 expression is highly associated with the remodeling of TME, which can be used as a potential biomarker to predict the efficacy of immunotherapy for non-metastatic colorectal cancer." (PMID 39980564, 2025). "HOXC6 was reported to be overexpressed in colorectal cancer and was associated with shorter survival of patients with hepatocellular carcinoma." (PMID 35547861, 2022). "Treatment with abemaciclib significantly downregulated HOXC6 mRNA expression in colorectal cancer cell lines." (PMID 40574852, 2025). "In colorectal cancer, the HOXC6 high-expression group exhibited typical EMT features, including downregulation of epithelial markers and upregulation of mesenchymal markers." (PMID 40574852, 2025). "Through an integrated approach combining computational drug screening and experimental validation, we systematically evaluated the therapeutic potential of HOXC6 in colorectal cancer." (PMID 40574852, 2025). "Wound healing assays and Trans-well migration assays showed that the migration rate was significantly lower in sh-HOXC6 cells compared to sh-NC cells, demonstrating that HOXC6 downregulation inhibits colorectal cancer cell migratory capacity." (PMID 40574852, 2025). "To investigate the effects of HOXC6 on colorectal cancer cell behaviors including proliferation, migration, and invasion, we established HOXC6-knockdown colorectal cancer cell lines." (PMID 40574852, 2025). "HOXC6 was also reported to be overexpressed in colorectal cancer tissue, and highly correlated with poor survival outcome and acts as a significant prognostic risk factor." (PMID 32957968, 2020). "In this study, we used a tissue microarray (TMA) consisting of 462 CRC samples to demonstrate that HOXC6 is more abundantly expressed in colorectal cancer (CRC) tissues than adjacent normal mucosa." (PMID 27081081, 2016). "In the present study, we found that HOXC6 was highly expressed in colorectal cancer compared to adjacent normal mucosa." (PMID 27081081, 2016). "These multi-level results, from molecular interactions to cellular phenotypes, collectively demonstrate that abemaciclib specifically targets HOXC6, forms stable complexes, and significantly inhibits colorectal cancer cell proliferation, migration, and invasion capabilities." (PMID 40574852, 2025). "A precedent study highlighted a significant correlation between elevated HOXC6 expression and the expression of chemokines that recruit T cells, the degree of immune cell infiltration, and the presence of immune checkpoint markers in colorectal cancer." (PMID 39138733, 2024). "A previous study highlighted overexpression f HOXC6 in tumor tissues of colorectal cancer." (PMID 30559605, 2018). "Thus, combining Abemaciclib with immunotherapy could improve treatment sensitivity in HOXC6-high colorectal cancer patients." (PMID 40574852, 2025). "Furthermore, Trans-well invasion assays conducted with these cell lines revealed a significant decrease in the number of cells penetrating through the membrane in the sh-HOXC6 group versus the sh-NC group, indicating that HOXC6 knockdown impairs the invasive capability of colorectal cancer cells." (PMID 40574852, 2025). "Homeobox C6 (HOXC6) is a transcription factor that plays a vital role in several cancers, including colorectal cancer." (PMID 35711425, 2022). "Among them, MMP12 was highly expressed in colorectal cancer tissues, while ARMCX2, CEBPA, CXCL13, FABP4, HOXC6, SIGLEC1 and VSIG4 were more expressed in normal tissues than in cancer tissues." (PMID 36544770, 2022). "The expression of CCKBR, HOXC6, and POU4F1 were significantly higher in colorectal cancer cell lines compared to those in FHC cells." (PMID 36176299, 2022).
glioma (14 papers, 2015 to 2025). A benign or malignant brain and spinal cord tumor that arises from glial cells (astrocytes, oligodendrocytes, ependymal cells). "HOXC6, frequently overexpressed in multiple cancers, including glioma, was associated with poor prognosis in glioblastoma patients." (PMID 37547473, 2023). "Overexpression of HOXC6 in glioma tissues and cell lines was linked to proliferation, clinical progression, and immune infiltrations." (PMID 37547473, 2023). "The biological role of HOXC6 in gliomas was primarily associated with EMT and the immune microenvironment in gliomas." (PMID 35488304, 2022). "Subsequently, we conducted verification tests to verify that HOXC6 upregulation is strongly associated with poor prognosis in patients with gliomas." (PMID 35488304, 2022). "In gliomas, Hoxc6 is highly expressed and associated with poor prognosis." (PMID 41154668, 2025). "We hypothesized that the association between HOXC6 overexpression and poor prognosis was influenced by the promotion of glioma proliferation and migration." (PMID 35571491, 2022). "Upregulated HOXC6 is an independent risk factor and predicts poor prognosis in glioma patients." (PMID 36118887, 2022). "HOXC6, WT1, CD70, and OTP expression was upregulated in glioma tissues from patients with high-risk scores." (PMID 38499392, 2024). "HOXC6, WT1, CD70, and OTP expression was elevated in glioma tissues from high-risk score patients carrying wild-type TERTp." (PMID 38499392, 2024). "Focusing on the TERTp-mutant glioma subtype, we developed an immune-related gene signature including HOXC6, WT1, CD70, and OTP that showed significant prognostic value for TERTp-mutant gliomas, but not for TERTp wild-type gliomas, in two TCGA cohorts." (PMID 38499392, 2024). "Based on multivariate Cox regression analysis, the immune signature created using HOXC6, WT1, CD70, and OTP represented an independent prognostic factor for glioma patients with TERTp mutations." (PMID 38499392, 2024). "Many HOMEOBOX (HOX)-related genes (HOXD11, HOXD9, HOXC10, HOXC11, HOXC6, HOXB3, HOXA2, HOXA1) were associated with a glioma grade and significantly overexpressed in GIV (Wilcoxon rank-sum and BH padj < 0.05)." (PMID 36850002, 2023). "We performed Gene Ontology (GO) analysis and gene set enrichment analysis (GSEA) based on ChIP-seq and public datasets to explore the biological characteristics of HOXC6 in gliomas." (PMID 35488304, 2022). "Then, the inhibitory effect of HOXC6 on the proliferation of U251 and U87 glioma cells was observed by the CCK-8 assay." (PMID 35571491, 2022). "By assessing individualized prognostic forecasts in the nomogram, we confirmed HOXC6 as a prognostic biomarker of glioma." (PMID 35488304, 2022). "The relationship between HOXC6 expression and prognosis in patients with gliomas was further analysed using our clinical samples, which illustrated that the high expression of HOXC6 was related to a short OS." (PMID 35488304, 2022). "The prognosis and survival rate of glioma patients with high HOXC6 expressions were significantly lower than those with low expression (p < 0.0001)." (PMID 35571491, 2022). "Gene profile data obtained from ONCOMINE, TCGA, GEPIA, and CGGA databases have been previously used to analyze and verify the expression of HOXC6 in gliomas and the impact of increased HOXC6 expressions on the poor prognosis of glioma patients." (PMID 35571491, 2022). "Second, we also need more animal models to validate our findings and advance the clinical application of HOXC6 as a glioma immunotherapy target." (PMID 35488304, 2022). "In the present study, we demonstrated that the poor prognosis of glioma patients was significantly and positively correlated with the HOXC6 expression." (PMID 35571491, 2022). "Bioinformatic and IHC analyses of collected samples (n = 299) were performed to detect HOXC6 expression and the correlation between HOXC6 expression and clinicopathological features of gliomas." (PMID 35488304, 2022).
glioma (continued). "Among them, 22 genes had a degree score ≥10 and 6 genes (WT1, HOXA2, HOXC6, MMP9, SHOX2 and MYOD1) were selected to construct a signature to classify glioma patients into low- or high-risk groups." (PMID 36118887, 2022). "The mechanistic analyses indicated that HOXC6 exerts its promotive effect on the progression and invasion of glioma cells by promoting the activation of the EMT and TGF-β/Smad signaling pathways." (PMID 35571491, 2022). "In the functional experiment, we showed that HOXC6 plays an important role in the proliferation and migration of gliomas." (PMID 35571491, 2022). "Then, HGG and LGG cases were analyzed together, and we concluded that, in gliomas, the prognosis and survival rate significantly decreased in patients with high expressions of HOXC6." (PMID 35571491, 2022). "A total of 81 glioma patients with high HOXC6 expressions were compared to 81 glioma patients with low HOXC6 expressions." (PMID 35571491, 2022). "For this, we analysed the protein expression level of HOXC6 in glioma tissues in 299 patient samples using IHC, which verified that the protein expression of HOXC6 was positively correlated with a high grade of glioma." (PMID 35488304, 2022). "Previous studies have shown increased expression of HOXC6 for multiple cancers, as well as its growth promotion ability in glioma cells." (PMID 35571491, 2022). "The HOXC6 knockdown and control cells (U87 glioma cells) were intratumorally injected into a subcutaneous transplanted tumor model." (PMID 35571491, 2022). "All these assays revealed that HOXC6 notably promotedcell proliferation in glioma cells, which demonstrated the correlation between low HOXC6 expression and good prognosis in gliomas." (PMID 35488304, 2022). "The expression of HOXC6, MMP9, SHOX2 and MYOD1 was associated with hypoxia degree in glioma tissues and in recurrent cases, had a remarkable diagnostic value and a significant relationship with disease free survival in glioma patients." (PMID 36118887, 2022). "A total of 111 glioma patients with high expressions of HOXC6 were compared to 111 with low expressions." (PMID 35571491, 2022). "In the Western blot experiments, we evaluated the levels of HOXC6 in six glioma cell lines and found that the levels of HOXC6 increased to varying degrees." (PMID 35571491, 2022). "Then, we structured the ROC curve on account of the clinical samples, TCGA, CGGA and Rembrandt datasets to explore the value of HOXC6 for glioma diagnosis according to the area under the ROC curve (AUC)." (PMID 35488304, 2022). "In our study, the Spearman correlation coefficients between HOXC6 and B7-H3 were 0.64 in TCGA gliomas and 0.55 in CGGA gliomas." (PMID 35488304, 2022). "HOXC6, which is associated with EMT and the immune microenvironment, is expected to be a potential therapeutic target for glioma." (PMID 35488304, 2022). "In the Transwell chamber invasion experiment, the reduction of HOXC6 in U87 and U251 glioma cells was indicated by microscopic photographs." (PMID 35571491, 2022). "IHC staining of primary and recurrent glioma tissues suggested that the expression of HOXC6, MMP9, MYOD1 and SHOX2 are associated with the degree of hypoxia in gliomas as well in recurrent cases." (PMID 36118887, 2022). "Then, we used the GEPIA database to identify the expression levels of HOXC6 in 163 high-grade gliomas (HGG, WHO: III-IV) and 207 normal brain tissues." (PMID 35571491, 2022). "Among the three groups of U87 and U251 glioma cells, the knockdown of HOXC6 using siRNA1 and siRNA2 suppressed cell proliferation compared to controls (p < 0.001)." (PMID 35571491, 2022). "In the present study, we found that HOXA5, HOXA7, HOXA10, HOXC4 and HOXC6 are prognostic markers in glioma patients." (PMID 28055976, 2017). "The upregulation of HOXA9, HOXC6, HOXC11, HOXD1, and HOXD8 expression is associated with the proliferation and growth of glioma." (PMID 26565624, 2015).
glioma (continued). "HOXC6, WT1, CD70, and OTP were highly expressed in high-risk vs. low-risk glioma samples." (PMID 38499392, 2024). "Additionally, the mIF in HPA revealed that HOXC4, HOXC5, and HOXC6 proteins were primarily expressed in nucleoplasm in the glioma cell line U-251MG." (PMID 37547473, 2023). "Moreover, through performing ROC analysis, we found that HOXC6, MMP9, SHOX2 and MYOD1 had a high diagnostic value (AUC>0.7) to distinguish primary and recurrent glioma tissues." (PMID 36118887, 2022). "Thus, to select cell lines for the next experiment, the gray value calculation showed that the levels of HOXC6 in U251 and U87 glioma cells lines were significantly higher compared to A172, T98G, H4, and SHG44 cells." (PMID 35571491, 2022). "Considering these results, we hypothesized that, in glioma tissue specimens, the expression of HOXC6 has a rising trend." (PMID 35571491, 2022). "The migration of U251 and U87 glioma cells was inhibited after HOXC6 knockdowns." (PMID 35571491, 2022). "Herein, the activation of the TGF-β/Smad pathway and subsequent phosphorylation of Smad proteins were impaired by HOXC6 silencing, suggesting that HOXC6 exerts its regulatory effect on the migrative and invasive capacity of glioma cells by promoting the activation of the TGF-β/Smad pathway." (PMID 35571491, 2022). "The IHC results confirmed our hypothesis; that is, HOXC6 expression increased in high-grade glioma patients." (PMID 35571491, 2022). "Herein, we demonstrated that HOXC6 was overexpressed in many cancers, especially in glioma." (PMID 35488304, 2022). "The proliferation and migration ability of U87 and U251 cells with HOXC6 knockdown were significantly reduced, which would be beneficial for the use of HOXC6 as a therapeutic target to improve the prognosis, survival rate, and quality of life of glioma patients." (PMID 35571491, 2022). "Therefore, we inferred that HOXC6 can act as a predictor for the clinical prognosis of glioma patients." (PMID 35488304, 2022). "Therefore, we transfected U87 and U251 glioma cells with RNAi and knocked down HOXC6 to study its effects on the proliferative and migrative capacities of glioma cells." (PMID 35571491, 2022). "HOXC6 was overexpressed and related to the clinicopathological features of gliomas." (PMID 35488304, 2022). "PD-L1 and B7-H3 expression levels were decreased in HOXC6 knockdown glioma cell lines." (PMID 35488304, 2022). "Furthermore, results analyzed in glioma tissues in the TCGA demonstrated that glioma patients with high expression levels of HOXC6, MMP9 and SHOX2 had lower dis-ease-free survival rates." (PMID 36118887, 2022). "Interestingly, results from glioma tissues in the TCGA also indicated that patients with high expression levels of HOXC6, MY-OD1 and SHOX2, and low expression levels of MYOD1, had a lower disease-free survival rate." (PMID 36118887, 2022). "Considering the emerging role of epigenetic regulators as targets for cancer therapy, we tested whether HOXC6 was differentially expressed in the context of gliomas." (PMID 35488304, 2022). "In this study, we downloaded HOXC6 expression data from The Cancer Genome Atlas (TCGA), the Chinese Glioma Genome Atlas (CGGA) and the Rembrandt database and analysed the abnormal expression and prognostic value of HOXC6 in glioma patients based on data from these publicly available databases." (PMID 35488304, 2022). "HOXC6 expression correlated positively with glioma grade in the TCGA dataset." (PMID 35488304, 2022). "However, there are few studies regarding the role of the HOXC6 gene in glioma cells, as well as in their occurrence and development." (PMID 35571491, 2022). "Furthermore, we analysed the significant changes in HOXC6 expression at the transcriptional level between different forms of brain and CNS cancers vs. normal brain tissues using the Oncomine database." (PMID 35488304, 2022). "Generally, HOXC6 plays a significant role in brain and CNS cancers." (PMID 35488304, 2022).